UBXN8 (UBX domain protein 8)
Description:
Involved in endoplasmic reticulum-associated degradation (ERAD) for misfolded lumenal proteins, possibly by tethering VCP to the endoplasmic reticulum membrane. May play a role in reproduction.
Synonyms: D8S2298E; REP8; UBXD6
Tractability: Antibody: UniProt predicts a signal peptide or a membrane-spanning region. PROTAC: ubiquitination databases record sites on it.
Gene: Protein-coding gene on chromosome 8 (30,729,131 to 30,767,009, forward strand). Ensembl gene ENSG00000104691.
Subcellular location: Endoplasmic reticulum membrane
Subcellular location (Human Protein Atlas): Endoplasmic reticulum; Nucleoli; Nucleoplasm
Gene Ontology:
Molecular function: protein binding; protein-macromolecule adaptor activity
Biological process: ERAD pathway; single fertilization
Cellular component: endoplasmic reticulum; endoplasmic reticulum membrane; ubiquitin ligase complex
Genetic constraint (gnomAD): Loss-of-function variants: 33 observed, 30.26 expected, observed/expected ratio (o/e) 1.09, 90% interval 0.83 to 1.46. The upper end of that interval is the gene's LOEUF score, 1.46, which puts it in group 6 of 6, group 1 being the genes least tolerant of losing a copy. Missense variants: 274 observed, 283.61 expected, observed/expected ratio (o/e) 0.97, 90% interval 0.88 to 1.07. Synonymous variants: 102 observed, 102.24 expected, observed/expected ratio (o/e) 1, 90% interval 0.85 to 1.18.
Homologues: Orthologues: chimpanzee UBXN8 (91% identical), macaque UBXN8 (89% identical), dog UBXN8 (83% identical), pig UBXN8 (79% identical), rat Ubxn8 (74% identical), mouse Ubxn8 (73% identical), guinea pig UBXN8 (67% identical), zebrafish ubxn8 (29% identical), Drosophila melanogaster Faf2 (17% identical), Caenorhabditis elegans H40L08.1 (13% identical). Paralogues in human: FAF1 (27% identical), FAF2 (20% identical), UBXN7 (19% identical), UBXN10 (13% identical).
Diseases named in the same sentence as UBXN8 in open-access papers:
UBXN8 is named in the same sentence as 5 diseases in open-access papers, as found by Europe PMC text mining. Sharing a sentence is not in itself a finding about the gene and the disease. The quoted sentences say what the papers report.
leukemia (1 paper, 2021). A malignant (clonal) hematologic disorder, involving hematopoietic stem cells and characterized by the presence of primitive or atypical myeloid or lymphoid cells in the bone marrow and the blood. "Overall, these results indicated that UBXN8 expression is selectively downregulated in RUNX1-RUNX1T1+ leukemia cells, suggesting that downregulated UBXN8 expression is controlled by RUNX1-RUNX1T1." (PMID 34921223, 2021). "This study also showed that the UBXN8 gene was specifically downregulated in RUNX1-RUNX1T1+ leukemia cell lines." (PMID 34921223, 2021). "In addition, decitabine, a specific inhibitor of DNA methylation, upregulated the expression of UBXN8 in RUNX1-RUNX1T1+ leukemia cell lines." (PMID 34921223, 2021). "Among the genes with varied methylation in RUNX1-RUNX1T1+ leukemia cells, UBXN8 has obvious hypermethylation at its promoter region, and evidence from several bioinformatic databases shows that UBXN8 is obviously downregulated in RUNX1-RUNX1T1+ leukemia, which garnered our attention." (PMID 34921223, 2021).
tumor (3 papers, 2016 to 2024). "Most members of UBXDF were upregulated in LIHC (p < 0.01), except for UBXN10 and UBXN8 (the two members with the lowest expression levels in the major tumours)." (PMID 38365777, 2024). "In vivo experiments demonstrated that ectopic expression of the UBXN8 gene can clearly decrease tumor proliferation and promote the expression of CD11b in mice engrafted with SKNO-1 cells, further confirming the in vitro results." (PMID 34921223, 2021). "Enhancing UBXN8 levels can significantly inhibit tumor proliferation and promote the differentiation of RUNX1-RUNX1T1+ cells in vivo." (PMID 34921223, 2021). "It has been reported that the UBXN8 gene encodes one of the p97 cofactors, but its role in tumor biology is not yet well characterized." (PMID 34921223, 2021). "Drugs that block these modifications and stimulate UBXN8 activity also arrest tumor cell division." (PMID 34921223, 2021).
UBXN8 also shares sentences with these, for which no sentence is quoted: acute myeloid leukemia (1 paper); cancer (1); hepatocellular carcinoma (1).